DSC2 (desmocollin 2)
Description:
A component of desmosome cell-cell junctions which are required for positive regulation of cellular adhesion. Promotes timely incorporation of DSG2 into desmosome intercellular junctions and promotes interaction of desmosome cell junctions with intermediate filament cytokeratin, via modulation of DSP phosphorylation. Plays an important role in desmosome-mediated maintenance of intestinal epithelial cell intercellular adhesion strength and barrier function. Positively regulates wound healing of intestinal mucosa via promotion of epithelial cell migration, and also plays a role in mechanotransduction of force between intestinal epithelial cells and extracellular matrix. May contribute to epidermal cell positioning (stratification) by mediating differential adhesiveness between cells that express different isoforms. May promote p38MAPK signaling activation that facilitates keratinocyte migration (By similarity).
Synonyms: CDHF2; DSC3; ARVD11; DG2; DGII/III
Tractability: Antibody: UniProt places it where antibodies can reach, with high confidence; its Gene Ontology location is reachable by antibodies, with high confidence; UniProt predicts a signal peptide or a membrane-spanning region; the Human Protein Atlas places it where antibodies can reach. PROTAC: ubiquitination databases record sites on it; its protein half-life has been measured.
Gene: Protein-coding gene on chromosome 18 (31,058,545 to 31,102,600, reverse strand). Ensembl gene ENSG00000134755.
Subcellular location: Cell membrane; Cell junction, desmosome
Subcellular location (Human Protein Atlas): Plasma membrane; Endoplasmic reticulum
Pathways (Reactome):
Developmental Biology: Formation of the cornified envelope; Keratinization
Gene Ontology:
Molecular function: protein binding; protein dimerization activity; calcium ion binding; cell adhesive protein binding involved in bundle of His cell-Purkinje myocyte communication
Biological process: bundle of His cell-Purkinje myocyte adhesion involved in cell communication; cardiac muscle cell-cardiac muscle cell adhesion; epithelial cell-cell adhesion; positive regulation of p38MAPK cascade; positive regulation of protein localization; positive regulation of wound healing; regulation of heart rate by cardiac conduction; regulation of ventricular cardiac muscle cell action potential; cell adhesion; cell-cell adhesion; homophilic cell-cell adhesion
Cellular component: cytoplasmic vesicle; desmosome; extracellular exosome; intercalated disc; plasma membrane; cornified envelope; adherens junction; cell junction; membrane
Genetic constraint (gnomAD): Loss-of-function variants: 53 observed, 89.65 expected, observed/expected ratio (o/e) 0.59, 90% interval 0.47 to 0.74. The upper end of that interval is the gene's LOEUF score, 0.74, which puts it in group 3 of 6, group 1 being the genes least tolerant of losing a copy. Missense variants: 1,038 observed, 1,115.7 expected, observed/expected ratio (o/e) 0.93, 90% interval 0.88 to 0.98. Synonymous variants: 375 observed, 400.1 expected, observed/expected ratio (o/e) 0.94, 90% interval 0.86 to 1.02.
Gene-disease validity (ClinGen):
ClinGen rates the evidence that DSC2 causes each of these diseases.
familial isolated arrhythmogenic right ventricular dysplasia (autosomal dominant): Definitive.
Homologues: Orthologues: chimpanzee DSC2 (99% identical), macaque DSC2 (96% identical), rabbit DSC2 (82% identical), pig DSC2 (82% identical), dog DSC2 (82% identical), mouse Dsc2 (76% identical), guinea pig DSC2 (76% identical), rat Dsc2 (72% identical), tropical clawed frog dsc3 (38% identical), zebrafish dsc2l (36% identical). Paralogues in human: DSC3 (66% identical), DSC1 (54% identical), DSG4 (29% identical), DSG3 (28% identical), DSG2 (26% identical), DSG1 (23% identical).
Diseases named in the same sentence as DSC2 in open-access papers:
DSC2 is named in the same sentence as 112 diseases in open-access papers, as found by Europe PMC text mining. Sharing a sentence is not in itself a finding about the gene and the disease. The quoted sentences say what the papers report.
arrhythmogenic right ventricular cardiomyopathy (17 papers, 2007 to 2026). "DSC2, encoding desmocollin 2, has been reported to be associated with arrhythmogenic right ventricular cardiomyopathy." (PMID 31464081, 2019). "Loss of Dsg2 is embryonically lethal while mutations in Dsg2 and Dsc2 cause arrhythmogenic right ventricular cardiomyopathy (ARVC), a hereditary heart disease." (PMID 29999492, 2018). "Loss-of-function mutations in DSC2 and other genes of the desmosome are associated with Arrhythmogenic Right Ventricular Cardiomyopathy (ARVC)." (PMID 25390934, 2014). "To our surprise, we discovered that one of our supercentenarians carried a known pathogenic allele in the DSC2 gene associated with arrhythmogenic right ventricular cardiomyopathy (ARVC)." (PMID 25390934, 2014). "Genetic variants in desmosomal proteins (e.g., PKP2, DSP, DSG2, DSC2) are strongly associated with arrhythmogenic right ventricular cardiomyopathy (ARVC), while mutations in sarcomeric and cytoskeletal genes (e.g., MYH7, LMNA, DES) are linked to hypertrophic and dilated cardiomyopathies." (PMID 41596321, 2026). "DSC2-related arrhythmogenic right ventricular cardiomyopathy (ARVC) is thought to generally be inherited in an autosomal dominant pattern and monoallelic inheritance is considered for ACMG SF reporting of DSC2-related ARVC." (PMID 41000626, 2025). "Various genes coding cytoskeleton proteins such as DSC2 (desmocollin-2) and DSG2 (desmoglein 2) have also been associated with DCM and arrhythmogenic right ventricular cardiomyopathy (ARVC)." (PMID 32005173, 2020). "Arrhythmogenic right ventricular cardiomyopathy (ARVC) is a rare but severe cardiac condition frequently associated with mutations of proteins involved in desmosomes (Plakophilin-2, Desmoplakin, Desmoglein-2, and Desmocollin-2), structures involved in the cell–cell interactions." (PMID 33329039, 2020). "The presence of multiple pathogenic variants in desmosomal genes (DSC2, DSG2, DSP, JUP, and PKP2) in patients with arrhythmogenic right ventricular cardiomyopathy (ARVC) has been linked to a severe phenotype." (PMID 37418234, 2023).
cardiomyopathy (14 papers, 2013 to 2025). A disease of the heart muscle or myocardium proper. "Despite the well-established role of its mutations in disease pathogenesis, effective therapeutic strategies for DSC2 mutation-induced cardiomyopathy have remained elusive." (PMID 40756361, 2025). "Patients with DSP-cardiomyopathy have a greater history of acute myocardial injury, while in a murine model, the overexpression of desmocollin-2 (DSC2) has been associated with myocardial inflammation and fibrotic remodeling." (PMID 38202158, 2023). "Here, we demonstrate for the first time that cardiac specific overexpression of DSC2 causes a severe cardiomyopathy in mice." (PMID 28339476, 2017). "Transgenic mice with a cardiac-specific overexpression of the human DSC2 developed severe cardiomyopathy shortly after birth, with significantly reduced fractional shortening and ejection fractions." (PMID 40004470, 2025). "Their findings demonstrated that a single injection of modified DSC2 mRNA effectively reversed cardiomyopathy, restored right ventricular function, and significantly prolonged survival in vivo." (PMID 40756361, 2025). "Furthermore, mutations in the desmocollin-2 gene may cause cardiomyopathy and related arrhythmias." (PMID 39253394, 2024). "Others are associated with cardiomyopathy, such as that observed in DMD and GRMD (desmocollin 2 – DSC2; desmoglein 2 – DSG2)." (PMID 27549615, 2016). "Therefore, we developed a mouse model overexpressing desmocollin-2 to determine its potential contribution to cardiomyopathy and intercellular adhesion pathology." (PMID 28339476, 2017). "Our example shows that the DSC2 pathogenic mutation rs397514042 did not cause a fatal cardiomyopathy during the proband’s over 110 years of life." (PMID 25390934, 2014). "In summary, overexpression of DSC2 in mice leads to the development of severe cardiomyopathy, whereas the gene knock-out in mice does not." (PMID 28339476, 2017). "Functional, structural and expression analyses of the DSC2 transgenic mice revealed cardiomyocyte necrosis, an acute inflammatory process, ECM remodeling and fibrotic replacement leading to decreased cardiac function and cardiomyopathy." (PMID 28339476, 2017).
colorectal cancer (11 papers, 1990 to 2025). A primary or metastatic malignant neoplasm that affects the colon or rectum. "For example, in colorectal cancer, DSC2 loss enhances tumour cell growth by altering the Akt/β-catenin signal pathway." (PMID 36927383, 2023). "A reduction in the expression of a desmosomal protein DSC2 has been associated with shortened survival, high-grade malignancy and lymph node positivity in pancreatic tumor, and a decrease in DSC2 in colorectal cancer has also been observed." (PMID 32498335, 2020). "Switching from desmocollin-2 to desmocillin-3 has been noted in colorectal cancer development and the methylation of the DSC3 promoter is a prognostic marker of colorectal cancer." (PMID 25929336, 2015). "As an additional technical validation step, we assayed four genes (APC, MACC1, DCC, and DSC2) that have been previously established to be differentially expressed between tumor and adjacent normal tissue in colorectal cancer." (PMID 22363440, 2012). "In this report, we show for the first time that Dsc2 protein expression is reduced in colorectal cancer, and that this is accompanied by de novo expression of Dsc1 and Dsc3." (PMID 17088906, 2006).
colon carcinoma (10 papers, 2013 to 2023). "In colon cancer, loss of Dsg2 leads to a compensatory increase in Dsc2 expression and the increased Dsc2 suppresses cell proliferation by inhibition of EGFR downstream signaling such as Src." (PMID 32989241, 2021). "Moreover, the loss of DSC2 promoted the proliferation of colon cancer cells." (PMID 36817446, 2023). "Desmoglein-2 (DSG2) and Desmocollin-2 (DSC2) are transmembrane proteins that regulate intercellular connections, contributing to desmosome assembly and playing an important role in colon cancer progression." (PMID 38069408, 2023). "Conversely, a reduction in the expression of DSC2 has been found in other cancers including colon cancer and urothelial carcinoma tissues, where its downregulation was associated with rapid migration and invasion." (PMID 35387118, 2022). "To further substantiate the functionality of the Dsg2 mAb, we performed dispase-based dissociation assays in a colon carcinoma cell line (Caco-2), in which Dsg2 is the only desmosomal cadherin expressed beside Dsc2." (PMID 23326495, 2013). "Double down-regulation of DSC2 and DSG2 saved the down-regulation of DSG2 alone on the growth inhibition of colon cancer cell lines, suggesting that down-regulation of DSC2 could promote the proliferation of colon cancer cells." (PMID 36367775, 2022). "A similar effect of DSC2 and DSG2 mediated cell adhesion on cell aggregation was detected in colon cancer spheroids." (PMID 36927383, 2023).
breast carcinoma (9 papers, 2015 to 2025). "The aim of this study was to investigate the potential of DSC2 at mRNA and protein level as a predisposing factor for breast cancer progression and the development of breast cancer metastases, in particular to the lung and brain." (PMID 36927383, 2023). "Studied brain metastasis samples including lung cancer, breast cancer, esophageal cancer and melanoma, and found that the mutation rate of DSC2 is very high, and it may be a new marker in the development of brain metastasis." (PMID 33912561, 2021). "Desmoglein 2, desmocollin 2 (DSC2) and plakophilin 1 (PKP1) have been recently linked to an increased metastatic potential of breast cancer cells by promoting cell clustering and enhanced survival during the tumour cell dissemination process." (PMID 36927383, 2023). "In the present study, we found that tumour DSC2 levels significantly influence the disease-free and overall survival of breast cancer patients, in particular for patients with primary tumours corresponding to the HER2 positive and TNBC molecular subgroups." (PMID 36927383, 2023). "In the present study, we describe the pro-metastatic role of the desmosomal protein desmocollin 2 (DSC2) in breast cancer." (PMID 36927383, 2023). "This study focused specifically on desmocollin 2 (DSC2)—a transmembrane cell anchoring protein—in primary breast cancer, for which the role in breast cancer metastases formation is still not completely understood." (PMID 36927383, 2023). "DSC2 mRNA levels were evaluated in 197 tumour samples of breast cancer patients using microarray data from our own cohort (see description in material and methods)." (PMID 36927383, 2023). "To assess the impact of DSC2 in breast cancer cells, we performed DSC2 knockdown in MDA-MB231-BR cells, which endogenously express a higher level of DSC2 than the parental cell line MDA-MB231." (PMID 36927383, 2023). "Our research has been able to show, for the first time, that higher levels of DSC2 in primary breast cancer tissue significantly influence disease progression and metastatic behaviour in HER2 positive and TNBC patients." (PMID 36927383, 2023). "In the present study, we have analysed the role of DSC2 as a prognostic and predictive factor for primary breast cancer and the development of breast cancer metastases." (PMID 36927383, 2023). "Association of ANP32E, DSC2, IL6ST and ANKRD30A mRNA expression with clinicopathological features in breast cancer cases from the second cohort." (PMID 35387118, 2022). "While DSC2 is involved in tumor progression and development in various types of cancer, it is known to be highly expressed in aggressive subtypes and to be correlated with poor survival outcome in patients with breast cancer." (PMID 38539508, 2024). "An interesting possibility for future research would be to expand the DSC2 analyses to circulating tumour cells and clusters, as well as pulmonary breast cancer metastases, in order to further clarify the potential of DSC2 as a breast cancer brain and pulmonary metastases marker for clinical use." (PMID 36927383, 2023). "Microarray gene expression analysis of 23 breast cancer metastases showed that the upregulation of DSC2 expression may contribute to lung metastasis as a part of a 6-gene signature." (PMID 35387118, 2022). "Together with DSC2, it is part of a six-gene signature predicting breast cancer lung metastasis." (PMID 26537449, 2015). "Of note, while high DSC2 levels showed worse survival in TNBC and HER2-positive breast cancer, it was shown to be reversed in HR-positive breast cancer." (PMID 38539508, 2024). "ANP32E along with desmocollin 2 (DSC2), UDP glycosyltransferase 8 (UGT8), Integrin subunit beta 8 (ITGB8) and Fermitin family member 1 (FERMT1) is found to predict lung metastasis of breast cancer patients and has been used as prognostic marker." (PMID 32257110, 2020).
breast carcinoma (continued). "We found a significantly higher DSC2 expression in the more aggressive molecular subtypes HER2-positive and TNBC than in luminal breast cancers, as well as a significant correlation between increased DSC2 expression and a shorter disease-free—also in multivariate analysis—and overall survival." (PMID 36927383, 2023). "Additionally, a recent experimental study of a breast cancer cell line revealed significantly greater expression of the DSC2 gene in HER2-positive patients and TNBC patients, and DSC2 overexpression was significantly correlated with shorter disease-free survival and overall survival." (PMID 38539508, 2024). "Thus, the role of DSC2 seems to be entity-specific, or even subtype-specific, as shown in our study with a clear negative prognostic value of DSC2 in HER2 positive and TNBC, yet no impact on survival for patients with luminal breast cancer." (PMID 36927383, 2023).
colitis (6 papers, 2006 to 2024). Inflammation of the colon. "Loss of Dsc2 (8/19) and de novo expression of Dsc1 (11/19) and Dsc3 (6/19) was also found in colorectal adenocarcinomas on a background of colitis." (PMID 17088906, 2006). "In tumours on a background of colitis, loss of Dsc2 was observed in eight of 19 specimens examined, and de novo expression of Dsc1 and Dsc3 was detected in 11 of 19 and six of 19 specimens respectively." (PMID 17088906, 2006). "Epithelial-specific KO of desmocollin-2 showed no increased barrier permeability during DSS-induced colitis; however, another study showed that a conditional-inducible KO of desmocollin-2 had impaired mucosal repair after recovery from DSS-induced colitis." (PMID 34943865, 2021). "In addition, research by Sven Flemming and colleagues discovered that mice with an inducible conditional knockdown of Dsc2 exhibited compromised mucosal repair following biopsy-induced colonic injury and recovery from dextran sulfate sodium-induced colitis." (PMID 39331858, 2024). "Downregulation of Dsc2 was also noticed in inflamed tissue in both human UC and murine colitis." (PMID 35456978, 2022). "Thus, deleting Dsc2 in mouse IEC did not vastly influence intestinal mucosal architecture, but induced a delayed recovery upon DSS-induced colitis or biopsy-induced colonic wounding." (PMID 35456978, 2022).
dilated cardiomyopathy (6 papers, 2013 to 2024). Cardiomyopathy which is characterized by dilation and contractile dysfunction of the left and right ventricles. "For example, mutations in JUP, DSP, PKP2, DSG2, DSC2, CTNNA3, CDH2, or PLN (all of them more abundant in LV) predominantly lead to arrhythmogenic right ventricular cardiomyopathy, and mutations in MYH7, HSPB7, NEXN and MYPN (also all more abundant in LV) lead to dilated cardiomyopathy." (PMID 32291283, 2020). "We examined plakophilin-2, desmoglein-2, desmocollin-2, plakoglobin and β-catenin protein expression levels from seven independent ARVD/C heart samples compared to two ischemic, five dilated cardiomyopathy and one healthy heart sample as controls." (PMID 24086444, 2013).
cardiocutaneous syndromes (5 papers, 2020 to 2025). "Other desmosomal gene variants in JUP, desmoplakin (DSP), and desmocollin 2 (DSC2) have been found in isolated cases of similar cardio-cutaneous syndromes in various parts of the world, from the Mediterranean to Argentina and Ecuador." (PMID 39877668, 2025). "Recessive variants in DSC2, which encodes a desmosomal cadherin desmocollin-2, are also associated with cardiocutaneous syndromes, in contrast to heterozygous mutations, which typically cause dominant ARVC (OMIM: 610476)." (PMID 36672924, 2023). "The reported variants associated with cardiocutaneous syndrome, in genes DSP, JUP, DSC2, KLHL24, GJA1, are classified by interpretation guidelines from the American College of Medical Genetics and Genomics." (PMID 36142674, 2022).